CNOT7 (CCR4-NOT transcription complex subunit 7)
Description:
Has 3'-5' poly(A) exoribonuclease activity for synthetic poly(A) RNA substrate. Its function seems to be partially redundant with that of CNOT8. Catalytic component of the CCR4-NOT complex which is one of the major cellular mRNA deadenylases and is linked to various cellular processes including bulk mRNA degradation, miRNA-mediated repression, translational repression during translational initiation and general transcription regulation. During miRNA-mediated repression the complex also seems to act as translational repressor during translational initiation. Additional complex functions may be a consequence of its influence on mRNA expression. Associates with members of the BTG family such as TOB1 and BTG2 and is required for their anti-proliferative activity.
Synonyms: CAF-1; CAF1; Caf1a; hCAF-1
Tractability: Small molecule: a high-quality ligand is known. PROTAC: ubiquitination databases record sites on it; its protein half-life has been measured; a small molecule that binds it is known.
Target class: Enzyme; Hydrolase
Gene: Protein-coding gene on chromosome 8 (17,224,966 to 17,247,726, reverse strand). Ensembl gene ENSG00000198791.
Subcellular location: Nucleus; Cytoplasm, P-body; Cytoplasm, Cytoplasmic ribonucleoprotein granule
Subcellular location (Human Protein Atlas): Nuclear bodies; Nucleoplasm
Pathways (Reactome):
Developmental Biology: M-decay: degradation of maternal mRNAs by maternally stored factors
Metabolism of RNA: Deadenylation of mRNA
Gene Ontology:
Molecular function: 3'-5'-RNA exonuclease activity; DNA-binding transcription factor binding; poly(A)-specific ribonuclease activity; protein binding; RNA exonuclease activity; transcription corepressor activity; nucleic acid binding; piRNA binding
Biological process: deadenylation-dependent decapping of nuclear-transcribed mRNA; defense response to virus; miRNA-mediated gene silencing by mRNA destabilization; negative regulation of cell population proliferation; negative regulation of DNA-templated transcription; negative regulation of gene expression; negative regulation of type I interferon-mediated signaling pathway; nuclear-transcribed mRNA poly(A) tail shortening; positive regulation of cell population proliferation; positive regulation of mRNA catabolic process; positive regulation of nuclear-transcribed mRNA catabolic process, deadenylation-dependent decay; positive regulation of nuclear-transcribed mRNA poly(A) tail shortening; positive regulation of viral genome replication; regulation of tyrosine phosphorylation of STAT protein; regulatory ncRNA-mediated gene silencing; piRNA-mediated gene silencing by mRNA destabilization
Cellular component: CCR4-NOT complex; cytoplasm; membrane; nuclear body; nuclear speck; nucleoplasm; nucleus; CCR4-NOT core complex; cytosol; P-body; cytoplasmic ribonucleoprotein granule
Genetic constraint (gnomAD): Loss-of-function variants: 3 observed, 30.37 expected, observed/expected ratio (o/e) 0.0988, 90% interval 0.044 to 0.25. The upper end of that interval is the gene's LOEUF score, 0.25, which puts it in group 1 of 6, group 1 being the genes least tolerant of losing a copy. Missense variants: 137 observed, 281.7 expected, observed/expected ratio (o/e) 0.49, 90% interval 0.42 to 0.56. Synonymous variants: 109 observed, 93.86 expected, observed/expected ratio (o/e) 1.16, 90% interval 0.99 to 1.36.
Homologues: Orthologues: chimpanzee CNOT7 (100% identical), dog CNOT7 (100% identical), guinea pig CNOT7 (100% identical), pig CNOT7 (100% identical), mouse Cnot7 (99% identical), rat Cnot7 (99% identical), tropical clawed frog cnot7 (97% identical), zebrafish cnot7 (95% identical), macaque CNOT7 (70% identical), Drosophila melanogaster Pop2 (68% identical), Caenorhabditis elegans ccf-1 (46% identical). Paralogues in human: CNOT8 (76% identical).
Diseases named in the same sentence as CNOT7 in open-access papers:
CNOT7 is named in the same sentence as 36 diseases in open-access papers, as found by Europe PMC text mining. Sharing a sentence is not in itself a finding about the gene and the disease. The quoted sentences say what the papers report.
breast cancer (11 papers, 2013 to 2025). A primary or metastatic malignant neoplasm involving the breast. "For example, a high level of expression of CNOT7 is associated with appreciably enhanced survival in lung and gastric cancers, although it has little effect in breast cancer." (PMID 33138308, 2020). "Recently, CNOT7 was found to be highly expressed in MCF7 cells (a human breast cancer cell line) relative to the normal BC cell line." (PMID 40806280, 2025). "Previously, CNOT7 was found to exert specific bio-functions in breast cancer, ovarian cancer, colorectal cancer, and other malignant tumors." (PMID 35156522, 2022). "The MMTV-PyMT transgenic mammary tumor model was bred to Cnot7 hemizygous knockout mice to produce PyMT+Cnot7+/- and PyMT+Cnot7 wild type mice." (PMID 26807845, 2016). "Overall these results are consistent with a major role of the deadenylase function of CNOT7 in modulating metastatic capacity of mammary tumor cell lines." (PMID 26807845, 2016). "Cnot7 was knocked down in three independent murine mammary tumor cell lines by stable transduction of short hairpin RNAs (shRNAs), resulting in reductions of protein and transcript abundance." (PMID 26807845, 2016). "Specifically, Caf1/Cnot7 promotes metastatic disease in a murine model of breast cancer." (PMID 39339346, 2024). "To determine whether CNOT7-mediated metastasis promotion was deadenylase-dependent, we stably expressed the wild type and a deadenylase-inactive point mutant (D40A) in mammary tumor cell lines." (PMID 26807845, 2016). "Global transcriptome analysis in 4T1 mammary tumor cells revealed only 293 expressed genes bearing all three RNA binding protein motifs, consistent with previous findings of only limited numbers of genes changing after Cnot7 knockdown." (PMID 26807845, 2016). "To extend the previous analysis, we included data from silencing of CNOT6, CNOT6L, CNOT7, and CNOT8 from another cell line, namely, MCF7 (derived from pleural effusion of breast carcinoma), based on previous studies." (PMID 35630580, 2022). "CNOT7 and its paralog CNOT8 can influence the stability of cell cycle-related genes MSMB, PMP22, and Cyclin G2 through their deadenylation ability, promoting cell proliferation in breast cancer." (PMID 41249119, 2025). "However, the role of Caf1/CNOT7 and Caf1/CNOT8 in the regulation of mRNA levels is essentially identical when studied in human breast cancer cells using knockdown approaches in combination with genome-wide expression profiling." (PMID 24391663, 2013).
osteosarcoma (3 papers, 2022 to 2025). A usually aggressive malignant bone-forming mesenchymal neoplasm, predominantly affecting adolescents and young adults. "In osteosarcoma, CNOT7-mediated m6A methylation regulates osteosarcoma proliferation, migration, and invasion." (PMID 41249119, 2025). "CNOT7 promoted cell proliferation, migration, and invasion of osteosarcoma cells." (PMID 38985240, 2025).
colorectal cancer (2 papers, 2022 to 2025). A primary or metastatic malignant neoplasm that affects the colon or rectum. "We detected the levels of CNOT7 in various colorectal cancer cell lines using western blotting and RT-qPCR, and selected HCT116 and SW480 cells for further experiments." (PMID 41249119, 2025).
glioma (2 papers, 2025). A benign or malignant brain and spinal cord tumor that arises from glial cells (astrocytes, oligodendrocytes, ependymal cells). "In glioma, CNOT7 is overexpressed and associated with poor prognosis, contributing to glioma progression through TNF-α and IL6-JAK-STAT3 pathways." (PMID 41249119, 2025). "The KM curve showed that high expression of CNOT7 was associated with poor prognosis of glioma patients." (PMID 38985240, 2025). "The cellular experiments indicated that knockdown of CNOT7 inhibited the proliferation, migration, and invasion of glioma cell line." (PMID 38985240, 2025). "The enrichment analysis revealed that the CNOT7 participated in the development of glioma via G2M checkpoint, E2F targets, IL6-JAK-STAT3, and TNF-α signaling pathways via NF-κB." (PMID 38985240, 2025). "The CNOT7 was positively correlated with transcription factors TOP2A or HDAC2 in glioma patients’ samples, especially HDAC2 (Spearmen = 0.42, Pearson = 0.41, R2 = 0.17)." (PMID 38985240, 2025). "First, through the TCGA database, we found that CNOT7 presented higher expression level in Glioblastoma multiforme (GBM) or Brain Lower Grade Glioma (LGG) samples compared with normal samples." (PMID 38985240, 2025). "Our studies have found that CNOT7 expression is significantly upregulated in glioma compared with normal group, including GBM and LGG." (PMID 38985240, 2025). "In the future, it is necessary to further expand the sample size and carry out multicenter cohort studies, and at the same time, to conduct more in-depth mechanism and preclinical studies on the specific role of CNOT7 in glioma." (PMID 38985240, 2025). "The cellular function experiments indicated that the knockdown of CNOT7 inhibited the proliferation, migration, and invasion of glioma cell line." (PMID 38985240, 2025). "As for the survival analysis of CNOT7, the higher expression of CNOT7 was present poorer prognosis in glioma." (PMID 38985240, 2025). "The analysis of GSEA and GSVA revealed that the CNOT7 participated in the development of glioma via G2M checkpoint, E2F targets, IL6-JAK-STAT3, and TNF-α signaling pathways via NF-κB." (PMID 38985240, 2025). "The TCGA (The Cancer Genome Atlas) and CGGA (Chinese Glioma Genome Atlas) databases were used for investigating the expression and survival condition of CNOT7 in glioma." (PMID 38985240, 2025). "In conclusion, CNOT7 is expected to be a possible therapeutic target for improving the clinical prognosis of glioma." (PMID 38985240, 2025). "According to the TCGA and CGGA databases, the CNOT7 was highly expressed in glioma and presented the poorer prognosis." (PMID 38985240, 2025). "These evidences suggest that the CNOT7 participated in the progression of glioma via regulating glioma-related signaling pathways." (PMID 38985240, 2025). "The knockdown of CNOT7 inhibited the proliferation, migration, and invasion of glioma cell line, compared to control group." (PMID 38985240, 2025). "The TCGA and the CGGA database were used for investigate the expression and survival condition of CNOT7 in glioma." (PMID 38985240, 2025). "The high-expressed CNOT7 is an oncogene with poor prognosis and participate the progression of glioma." (PMID 38985240, 2025). "Besides, it was found that the HDAC2 (Human histone deacetylase-2) contributes to increased CNOT7 expression in glioma." (PMID 38985240, 2025). "The CNOT7 was highly expressed in glioma and presented the poorer prognosis." (PMID 38985240, 2025). "It was found that CNOT7 is a candidate oncogene and poor prognostic biomarker in glioma." (PMID 38985240, 2025). "Then, we sequentially explored the molecular mechanism of CNOT7 in glioma." (PMID 38985240, 2025). "Together, these results indicated that CNOT7 is highly expressed with poor prognosis in glioma, which suggest that it might be a potential oncogene in glioma." (PMID 38985240, 2025). "In this study, we aimed to explore the function of CNOT7 in glioma." (PMID 38985240, 2025).
glioma (continued). "Our work is the first attempt to explore the role of CNOT7 in glioma." (PMID 38985240, 2025). "Finally, it was found that HDAC2 contributes to increased CNOT7 expression in glioma." (PMID 38985240, 2025). "These evidences revealed that the high-expressed CNOT7 is an oncogene with poor prognosis and participated in the progression of glioma, and HDAC2 upregulated CNOT7 expression." (PMID 38985240, 2025). "In this study, we found that the HDAC2 was positive-correlated with the expression of CNOT7, HDAC2 upregulated CNOT7 expression in glioma cells." (PMID 38985240, 2025). "The CNOT7 (CCR4-NOT Transcription Complex Subunit 7) is an important functional subunit of CCR4-NOT protein complex that has not been reported in glioma." (PMID 38985240, 2025). "In this research, it was the first time to investigate and verify the function of CCR4-NOT protein complex CNOT7 in glioma." (PMID 38985240, 2025). "CNOT7 regulates the progression of glioma by affecting the E2F targets, G2/M checkpoint, TNF-α and IL6-JAK-STAT3 signaling pathway through NF-κB, leading to poor prognosis in glioma." (PMID 41249119, 2025). "To date, the function of CNOT7 in glioma has not been investigated." (PMID 38985240, 2025). "However, the expression and function of CNOT7 in glioma has not been reported yet." (PMID 38985240, 2025).
Obesity (2 papers, 2018 to 2025). Accumulation of substantial excess body fat. "A previous study found over expressions of the Cnot7 gene in the livers of mice induced with obesity through a high-fat diet." (PMID 29942931, 2018). "In obese conditions, knockout mice of CNOT7, a deadenylase subunit in the complex, were resistant to HFD-induced obesity in mice due to increased energy expenditure driven by up-regulated mRNA level of uncoupling protein 1 (Ucp1) in WATs." (PMID 40424271, 2025). "Previous reports on gene knockout mice of CCR4-NOT components, such as CNOT3, CNOT6L and CNOT7, have demonstrated that CCR4-NOT complex plays roles in suppressing diet-induced obesity and improving metabolic disorder through degradation of target mRNAs." (PMID 40424271, 2025).
ovarian carcinoma (2 papers, 2022 to 2025). A malignant neoplasm originating from the surface ovarian epithelium. "For instance, CNOT7 modulates biological functions of ovarian cancer cells via AKT signaling pathway." (PMID 38985240, 2025). "CNOT7 has been reported to be related to some tumors, such as ovarian cancer, breast cancer, and colorectal cancer." (PMID 38985240, 2025).
viral infection (2 papers, 2018 to 2021). "Similarly, CNOT7 and ADAP2, both down-regulated in severe malaria, were previously reported to have a protective role during viral infections." (PMID 34746025, 2021).
acute myeloid leukemia (1 paper, 2014). Acute myeloid leukemia (AML) is a group of neoplasms arising from precursor cells committed to the myeloid cell-line differentiation. "The expression of CNOT6L and CNOT7 was reportedly down-regulated in samples of leukemia cells taken from ALL and AML (acute myeloid leukemia) patients compared to normal blood cells, while the expression of CNOT6 was slightly up-regulated." (PMID 25191340, 2014).
adenovirus infection (1 paper, 2018). "The levels of at least 2 other members of the complex (CNOT3 and CNOT7) are also reduced during adenovirus infection, whereas the levels of CNOT4 and CNOT1 remain stable." (PMID 29593045, 2018).
Arrhythmia (1 paper, 2020). Any cardiac rhythm other than the normal sinus rhythm. "Furthermore, the cardiac-specific knockdown of Drosophila orthologs of CCR4-NOT genes in vivo (CNOT1/Not1 and CNOT7/8/Pop2) was either lethal or resulted in dilated cardiomyopathy, reduced contractility or a propensity for arrhythmia." (PMID 32471864, 2020).
cataract (1 paper, 2025). Partial or complete opacity of the crystalline lens of one or both eyes that decreases visual acuity and eventually results in blindness. "Reassuringly, as part of this study we identified several gene pairs such as SLC25A37/SLC25A28 and CNOT7/CNOT8 that represent attractive targets for further drug development, with Slc25a28 knockout mice being viable and fertile with no overt phenotypes, other than cataracts in some mice." (PMID 40968372, 2025).
cervical cancer (1 paper, 2019). A primary or metastatic malignant neoplasm involving the cervix. "The mean levels of CNOT7, PAX5, and SPDEF are slightly elevated in CESC samples compared with those in healthy tissue, though not significantly, while the level of TGM2 is significantly downregulated in cervical cancer." (PMID 30918060, 2019).
Cirrhosis (1 paper, 2020). A chronic disorder of the liver in which liver tissue becomes scarred and is partially replaced by regenerative nodules and fibrotic tissue resulting in loss of liver function. "To test this hypothesis, we examined the correlation between CNOT7, STAT1, TGF‐β1 and IFN‐γ expression with hepatitis B virus‐related cirrhosis and HCC with hepatitis B virus‐related cirrhosis." (PMID 32160402, 2020).
Dengue virus infection (1 paper, 2022). "Furthermore, CNOT2 supports Dengue virus infection by inhibiting JAK-STAT antiviral signaling via its interaction with CNOT6/6L and CNOT7/8 deadenylases." (PMID 36140672, 2022).
diabetes mellitus (1 paper, 2025). A metabolic disorder characterized by abnormally high blood sugar levels due to diminished production of insulin or insulin resistance/desensitization. "Moreover, we observed an almost significant positive association between diabetes mellitus and high expression of CNOT7; this result is consistent with a previous study stating that CNOT7 knockdown enhanced insulin sensitivity and glucose clearance." (PMID 40806280, 2025).
hepatic cancers (1 paper, 2025). "Similar data were obtained in hepatic cancers cells (i.e., HepG2) and, conversely, the CNOT7 deficiency decreases the TGFβ level and NFκB signaling and induces STAT1 expression." (PMID 39941720, 2025). "For instance, in hepatic cancer cells (i.e., HepG2), the AKT inhibitor triciribine triggers the ERK/RSK1 pathway, which phosphorylates BRF1 and reduces its binding to CNOT7, thereby increasing the stability of low-density lipoprotein receptor mRNAs." (PMID 39941720, 2025).
hepatocellular carcinoma (1 paper, 2020). A malignant tumor that arises from hepatocytes. "Natural killer (NK) cell resistance has been suggested as a primary cause of poor prognosis in hepatocellular carcinoma (HCC), which seemingly correlates with CNOT7 overexpression." (PMID 32160402, 2020). "Natural killer (NK) cell resistance is a primary cause of poor prognosis in hepatocellular carcinoma (HCC), which correlates with CNOT7 overexpression." (PMID 32160402, 2020).
infertile (1 paper, 2021). "Cnot7 knockout male mice have been reported to be infertile." (PMID 34026442, 2021).
lung adenocarcinoma (1 paper, 2024). A carcinoma that arises from the lung and is characterized by the presence of malignant glandular epithelial cells. "Likewise, CNOT8 protein levels were inversely correlated with CNOT7 copy numbers in patients with lung adenocarcinoma (LUAD) and BRCA in the NCI Clinical Proteomic Tumor Analysis Consortium cohort." (PMID 39009815, 2024).
malaria (1 paper, 2021). Malaria is a serious and sometimes fatal disease caused by a parasite that commonly infects a certain type of mosquito which feeds on humans. "The severe malaria K-TSPs model identified ten gene pairs capable of differentiating severe from non-severe malaria including: SLC38A2-SCML1, SLC25A40-MAP2K7, DNALI1-AGPAT3, LIFR-TBCD, STK17B-ORC2, SF3B1-USP48, ZNF148-ZCCHC2, CBX5-CHAF1A, CNOT7-PLXNA2, and CREM-IDH1." (PMID 34746025, 2021).
metastatic disease (1 paper, 2016). "Overall the ambiguous results of the in vitro assays suggested that further investigations into the mechanisms of the role of Cnot7 in metastatic disease would be best examined in vivo." (PMID 26807845, 2016). "Here we demonstrate that one of the enzymatic components of the CCR-NOT complex, Cnot7, is also a metastasis-associated gene, and that enzymatic activity of Cnot7 is required for its promotion of metastatic disease." (PMID 26807845, 2016). "Importantly, due to the multifunctional nature of the CCR4-NOT complex, the ability of Cnot7 to promote metastatic disease was dependent on deadenylase activity." (PMID 26807845, 2016).